ID3 (inhibitor of DNA binding 3)
Description:
Transcriptional regulator (lacking a basic DNA binding domain) which negatively regulates the basic helix-loop-helix (bHLH) transcription factors by forming heterodimers and inhibiting their DNA binding and transcriptional activity. Implicated in regulating a variety of cellular processes, including cellular growth, senescence, differentiation, apoptosis, angiogenesis, and neoplastic transformation. Involved in myogenesis by inhibiting skeletal muscle and cardiac myocyte differentiation and promoting muscle precursor cells proliferation. Inhibits the binding of E2A-containing protein complexes to muscle creatine kinase E-box enhancer. Regulates the circadian clock by repressing the transcriptional activator activity of the CLOCK-BMAL1 heterodimer.
Synonyms: bHLHb25; HEIR-1
Tractability: PROTAC: ubiquitination databases record sites on it.
Gene: Protein-coding gene on chromosome 1 (23,557,917 to 23,559,883, reverse strand). Ensembl gene ENSG00000117318.
Subcellular location: Nucleus
Subcellular location (Human Protein Atlas): Nucleoplasm
Pathways (Reactome):
Signal Transduction: NGF-stimulated transcription
Gene Ontology:
Molecular function: protein binding; transcription corepressor activity; transcription regulator inhibitor activity; bHLH transcription factor binding; leptomycin B binding; protein dimerization activity; protein domain specific binding
Biological process: negative regulation of DNA-templated transcription; negative regulation of transcription by RNA polymerase II; neuron differentiation; central nervous system development; circadian rhythm; metanephros development; negative regulation of myoblast differentiation; notochord development; odontogenesis; positive regulation of apoptotic process; positive regulation of gene expression; regulation of DNA replication
Cellular component: nucleoplasm; nucleus; cytoplasm
Genetic constraint (gnomAD): Loss-of-function variants: 3 observed, 8.96 expected, observed/expected ratio (o/e) 0.33, 90% interval 0.15 to 0.87. That is too few expected variants to judge how well the gene tolerates losing a copy. Missense variants: 168 observed, 155.62 expected, observed/expected ratio (o/e) 1.08, 90% interval 0.95 to 1.23. Synonymous variants: 97 observed, 71.67 expected, observed/expected ratio (o/e) 1.35, 90% interval 1.15 to 1.6.
Homologues: Orthologues: chimpanzee ID3 (99% identical), dog ID3 (99% identical), rabbit ID3 (99% identical), macaque ID3 (97% identical), mouse Id3 (97% identical), guinea pig ID3 (96% identical), pig ID3 (96% identical), rat Id3 (96% identical), tropical clawed frog id3 (56% identical), zebrafish id3 (50% identical), Drosophila melanogaster emc (29% identical). Paralogues in human: ID2 (46% identical), ID4 (45% identical), ID1 (41% identical).
Diseases named in the same sentence as ID3 in open-access papers:
ID3 is named in the same sentence as 166 diseases in open-access papers, as found by Europe PMC text mining. Sharing a sentence is not in itself a finding about the gene and the disease. The quoted sentences say what the papers report.
breast cancer (31 papers, 2009 to 2024). A primary or metastatic malignant neoplasm involving the breast. "In breast cancer, silencing both Id1 and Id3 caused a significantly greater reduction in tumor initiation and lung colonization than knockdown of either Id1 or Id3 alone." (PMID 23593444, 2013). "Among these members, ID1 has been implicated in EMT in breast cancer; the involvement of ID3 in EMT remains unclear." (PMID 39256881, 2024). "In addition, Id3 and Timp2 are associated with breast cancer metastasis and mammary gland differentiation." (PMID 27711132, 2016). "Unlike ID4, other members of the ID protein family (e.g., ID1 and ID3) are highly expressed in metastatic human breast cancers and exhibit pro-metastatic activity." (PMID 38188675, 2023). "ID1 and ID3 proteins are functionally redundant and have been shown to promote breast cancer cell self-renewal, tumor cell dissemination, and metastatic colonization of the lung and tumor re-initiation." (PMID 36207293, 2022). "Id3, often in concert with Id1, is essential for the self-renewal of tumor-initiating cells in several malignancies including glioma, breast cancer, and colon cancer." (PMID 34785704, 2021). "A number of studies have implied a significant role for ID1 and ID3 in breast cancer progression and metastasis." (PMID 32766238, 2020). "A peptide aptamer (Id1/Id3-PA7) has been developed, which induces cell cycle arrest and apoptosis in ovarian and breast cancer cells by inhibition of Id1 and Id3." (PMID 28122577, 2017). "In breast cancer Myc up-regulates Id3 that supports the entry in the S-phase by enhancing the cyclin/Cdk activity." (PMID 28122577, 2017). "We excluded an exclusive relationship between Dies1 and BMP-signalling in the breast cancer model by assessing the expression of ID2/ID3, as these genes were systematically downregulated independently of Dies1 expression." (PMID 27721458, 2016). "Previous studies on breast cancer demonstrated that Id1 and Id3 promote malignant progression by inhibiting apoptosis of cancer cells." (PMID 25061504, 2014). "In breast cancer, Id1 and Id3 are expressed predominately in triple negative tumors (estrogen -, progesterone -, and Her2Neu-)." (PMID 23593444, 2013). "Observations have suggested heterogeneity in Id1 and Id3 possibly due to high degree of sequence similarity: both Id1 and Id3 are required for neurogenesis, angiogenesis, and vascularization of tumor xenografts and involved in breast cancer lung metastasis." (PMID 23342268, 2012). "Four of the top 20 genes are upregulated in cancer stem cells, including Id3 in cancer stem cells of a mouse mammary tumor model and ID3 in intrahepatic cholangiocarcinoma tumors; MGST1 in human pancreatic cancer stem cells; and GPX3 and GSN in quiescent colon cancer stem cells." (PMID 36142331, 2022). "The Id proteins are also regulated through TGF-β signaling and similar to observations in the metastatic tumor model where Id3 was reduced in bcl-3−/− mammary tumors, bcl-3 null mammary glands were devoid of Id3 expression at involution, while expression was strongly increased in WT glands." (PMID 35681213, 2022). "The Inhibitor of Differentiation Protein 1 (Id1) and its closely related family member Inhibitor of Differentiation 3 (Id3) (collectively termed Id) are expressed by a diversity of stem cells and are required for metastatic dissemination in experimental models of breast cancer." (PMID 32766238, 2020). "In the breast cancer cell line MDA-MB-231, the genes ID2 and ID3 have been demonstrated to be under the control of P-TEFb, and reduced P-TEFb recruitment/activity has been suggested to underlie downregulated expression of ID2 and ID3 upon MEPCE depletion." (PMID 31467394, 2019). "FHL2- is a member of the four-and-a-half-LIM-only protein family, found over-expressed in BC cell lines upon DAC; it can inhibit the proliferation and invasive growth of human breast cancer cells by repressing the functional activity of an inhibitor of DNA binding 3 (ID3)." (PMID 25077705, 2014).
breast cancer (continued). "Moreover, functional studies have shown that Id1 and Id3 are required for both, tumor initiation and during metastatic colonization of the lung microenvironment by breast cancer cells." (PMID 23311395, 2013). "Based on the analysis of scRNA-seq and bulk RNA-seq data, we built and validated a cancer fibroblast-related risk signature consisting of five genes (BGN, LUM, CCL19, CEBPD, and ID3) that may be utilized as an independent prognostic indicator for breast cancer patients." (PMID 36510567, 2022). "As a tumor suppressor, TGF-β reduces the breast cancer stem cell population, and cell proliferation via MYC, ID1, and ID3 genes." (PMID 36207293, 2022). "A similar peptide aptamer–based approach targeting both Id1 and Id3 (Id1/3-PA7) was shown to induce cell cycle arrest and apoptosis in breast cancer cells MCF7 and MDA-MB-231." (PMID 23342268, 2012). "It was also shown that inhibiting ID1 and ID3 did not affect breast cancer cells’ capacity to migrate to the lung." (PMID 38195969, 2024). "To identify downstream target gene(s) that enhance stem-like features in breast cancer, we ranked ZNF148 ChIP-enrichment scores, and the expression fold changes of genes within the enriched GO terms and identified Inhibitor of DNA binding 3 HLH protein (ID3) as a potential candidate." (PMID 36207293, 2022). "However, the Id1/Id3 aptamer (Id1/3-PA7) has been shown to induce cell cycle arrest and apoptosis in breast cancer cells." (PMID 25693514, 2015). "In addition, when Id1 and Id3 are both interfered by Id1/3-PA7, an antiproliferative and apoptotic effect can be observed in breast cancer cells." (PMID 23311395, 2013). "To identify the other potential cellular pathways contributing to TAIII cytotoxicity in tumor cells, we examined the functional role of Id-1 that, along with Id-3 is strongly downregulated in breast cancer cells but not in MCF10A." (PMID 19789631, 2009).
Burkitt lymphoma (20 papers, 2014 to 2025). A rare form of malignant mature B-cell non-Hodgkin lymphoma. "Genetic alterations of ID3 in cancers are generally rare, and are most frequently seen in Burkitt lymphoma, and less commonly in various solid tumors as mutations, amplifications, and deletions." (PMID 33801781, 2021). "In Burkitt lymphoma, mutations involving ID3 are one of the more common neoplastic genetic alterations, occurring in 40% to 58% of cases." (PMID 33801781, 2021). "Mutations in ID3 have been shown to increase cell cycle progression and the expression of proliferation-associated genes in Burkitt lymphoma." (PMID 33801781, 2021). "Burkitt lymphoma bearing ID3 alteration tends to have at least two ID3 mutations, on separate alleles, consistent with the tumor suppressor function of ID3." (PMID 33801781, 2021). "Accordingly, Id3 mutations have been observed in more than 50% of all Burkitt lymphomas, and the presence of Id3 and/or TCF3 mutations has been detected in 70% of sporadic Burkitt lymphomas." (PMID 28122577, 2017). "Mice depleted for Id2 and Id3 expression developed colitis and αβ T-cell lymphomas, and the transcription signatures of Id2- and Id3-depleted lymphomas revealed similarities to genetic deficiencies associated with Burkitt lymphoma." (PMID 25691468, 2015). "Transcription signatures of Id2- and Id3-depleted lymphomas revealed similarities to genetic deficiencies associated with Burkitt lymphoma." (PMID 25691468, 2015). "Our data indicated for the first time that ID3 (recurrently mutated in Burkitt lymphomas) can be targeted through TFBS mutations in its promoter region." (PMID 25903198, 2015). "In addition, Id3 is identified as a tumor suppressor gene for Burkitt's lymphoma, as inactivating mutations occur in 68% of cases 11,14." (PMID 25693514, 2015). "•EBV-negative Burkitt lymphoma is more dependent on ID3/TCF3/CCND3 axis deregulation compared to EBV-positive Burkitt lymphoma." (PMID 41297313, 2025). "TSPAN32 expression is significantly downregulated in endemic, sporadic, and HIV‐associated Burkitt Lymphoma, and it is regulated by the TF3/ID3 pathway." (PMID 40572059, 2025). "In Burkitt lymphoma missense mutations of Id3 have been found, which lead to mutated HLH domain and altered ability of Id3 to inhibit TCF3 and/or TCF4." (PMID 28122577, 2017). "It is now established that the development of Burkitt lymphoma is closely associated with high levels of c-Myc expression and mutations localized across the HLH region of Id3." (PMID 25691468, 2015). "In Burkitt lymphoma by contrast, the function of the ID3 protein is recurrently inactivated through the acquisition of missense mutations in the ID3 gene, predominantly affecting the helix-loop-helix dimerisation domain." (PMID 25644253, 2015). "In addition, variants were detected in ID3 and IGLL5, two genes recurrently mutated in Burkitt lymphoma." (PMID 35205758, 2022). "As expected, mutations in frequent drivers such as CREBBP, KMT2D,TNFRSF14 and RRAGC were more frequent among follicular lymphomas, those of MYC, CCND3 and ID3 prevailed among Burkitt lymphoma and those of BTG2, PIM1, SGK1 and SOCS1 were more frequent among DLBCL." (PMID 33945543, 2021).
Burkitt lymphoma (continued). "In RAJI cells (Burkitt lymphoma) and SLVL cells (splenic B cell lymphoma), mutations of DNA-binding protein inhibitor ID-3 (ID3), transcription factor 3 (TCF3), and neurogenic locus notch homolog protein 2 (NOTCH2) increase phosphorylation of proteins in Akt/mTOR pathway." (PMID 33490663, 2021). "Some key findings include the predominance of ID3 mutations in Burkitt lymphoma, but not in other IGH-MYC rearranged lymphomas, as well as the role of aberrant somatic hypermutation (aSHM) in Epstein-Barr positive Burkitt Lymphomas." (PMID 33945543, 2021). "However, the ability of wild type ID3 to decrease cell proliferation in Burkitt lymphoma suggests ID3 mimetics may be a potential therapeutic approach in this disease process." (PMID 33801781, 2021). "A recent study reports an integrative analysis of driver gene mutations and gene expression profiles of Burkitt lymphomas (BL) and the authors identified ID3 as one of the BL driver genes." (PMID 34718742, 2021). "In particular ID3 mutations occurred in 34% of Burkitt’s lymphomas and not in DLBCLs." (PMID 25364378, 2014). "Moreover, inducing the expression of the I107R mutant with Dox in Burkitt lymphoma Namalwa cells resulted in impaired cell proliferation and the repression of Pax5, CIITA, and ID3." (PMID 28842558, 2017).
colon cancer (20 papers, 2013 to 2025). "ID3 promotes the maintenance of cancer stemness and is associated with poor treatment outcomes in colon cancer and cholangiocarcinoma." (PMID 35406487, 2022). "This is in accordance with the reported hypersensitivity of ID3-deficient colon cancer-initiating cells to the cisplatin analog oxaliplatin." (PMID 34718742, 2021). "In contrast, 3/4 colon cancer cell lines exhibited ID2 or ID3 expression loss concomitantly with Dies1 downregulation." (PMID 27721458, 2016). "Both ID1 and ID3 regulate self-renewal of colon cancer stem cells and play a role in resistance to the chemotherapy drug oxaliplatin." (PMID 38195969, 2024). "The results of these experiments provided evidence that ID1 and ID3 function together to control the self-renewal of colon cancer stem cells through cell-cycle restriction driven by the cell-cycle inhibitor p21." (PMID 29652830, 2018). "Colon cancer stem cells exhibited high ID1/ID3 expression and p21 expression; the knockdown of ID1/ID3 decreased p21 expression and decreased the tumorigenic potential of colon cancer stem cells." (PMID 29652830, 2018). "In primary colon cancer samples Id1 and Id3 regulate the self-renewal of colon cancer stem cells (CSCs) via p21." (PMID 28122577, 2017). "The previous study showed that Id1/Id3 regulates colon cancer-initiating cells (CC-ICs) by p21, and that, in colon cancer, Id1/Id3 protects the tumor-initiating ability of CC-ICs from oxaliplatin." (PMID 28143562, 2017). "Silencing of Id1 and Id3 together decreased self-renewal and increased sensitivity to chemotherapeutics of colon cancer-initiating cells." (PMID 24160469, 2013). "ID1 and ID3 regulate the self-renewal of colon cancer stem cells through p21." (PMID 38195969, 2024). "Consistent with the results of clonogenesis and proliferation assays, flow cytometry showed that radiation increased apoptosis of colon cancer cells after ID3 knockdown, suggesting that ID3 knockdown might increase the radiosensitivity of colon cancer cells." (PMID 37170184, 2023). "Importantly, the silencing of ID1 and ID3 increases the sensitivity of colon cancer stem cells to chemotherapeutic agents such as oxaliplatin." (PMID 29652830, 2018). "In colon cancer, it has been demonstrated that ID1 and ID3 expression collaborate to regulate cancer stem cell self-renewal through cell cycle restriction mediated by the cell cycle inhibitor p21." (PMID 39676870, 2024). "In colon cancer stem cells, the combined expression of ID1 and ID3 promotes self-renewal and tumor initiation." (PMID 38195969, 2024). "It has been reported that ID1 and ID3 govern self-renewal and cell cycle restriction on cancer stem cell (CSC) populations of colon cancer through regulation of p21." (PMID 27650540, 2016). "Notably, previous studies have shown that ID1, ID3, and c-MYC help maintain the self-renewal capacity of colon cancer stem cells." (PMID 40399276, 2025). "Moreover, PAF1 knockdown decreased the expression levels of the genes such as LGR5, ID1, ID3, CD44v9, CD133, BMI1, RNF43, EPHB2, SOX9, and ASCL2, which are critical for inducing colon cancer stemness and its markers." (PMID 38182897, 2024). "Recently, Id1 and Id3 co-expression (but not its individual expression) has been proposed as a novel mechanism of regulation of the self-renewal capacity of human colon cancer-initiating cells (CC-ICs)." (PMID 23311395, 2013).